NKIRAS1 (NFKB inhibitor interacting Ras like 1)
Description:
Atypical Ras-like protein that acts as a potent regulator of NF-kappa-B activity by preventing the degradation of NF-kappa-B inhibitor beta (NFKBIB) by most signals, explaining why NFKBIB is more resistant to degradation. May act by blocking phosphorylation of NFKBIB and mediating cytoplasmic retention of p65/RELA NF-kappa-B subunit. It is unclear whether it acts as a GTPase. Both GTP- and GDP-bound forms block phosphorylation of NFKBIB.
Synonyms: KappaB-Ras1; KBRAS1
Tractability: PROTAC: ubiquitination databases record sites on it; its protein half-life has been measured.
Gene: Protein-coding gene on chromosome 3 (23,889,951 to 23,946,591, reverse strand). Ensembl gene ENSG00000197885.
Subcellular location: Cytoplasm
Subcellular location (Human Protein Atlas): Cytosol; Endoplasmic reticulum
Pathways (Reactome):
Immune System: RIP-mediated NFkB activation via ZBP1; TAK1-dependent IKK and NF-kappa-B activation; TRAF6 mediated NF-kB activation
Gene Ontology:
Molecular function: GTPase activating protein binding; GTPase activity; GTP binding
Biological process: negative regulation of canonical NF-kappaB signal transduction; Ral protein signal transduction
Cellular component: cytosol; cytoplasm
Genetic constraint (gnomAD): Loss-of-function variants: 14 observed, 19.4 expected, observed/expected ratio (o/e) 0.72, 90% interval 0.48 to 1.13. The upper end of that interval is the gene's LOEUF score, 1.13, which puts it in group 4 of 6, group 1 being the genes least tolerant of losing a copy. Missense variants: 181 observed, 227.78 expected, observed/expected ratio (o/e) 0.79, 90% interval 0.7 to 0.9. Synonymous variants: 88 observed, 81.97 expected, observed/expected ratio (o/e) 1.07, 90% interval 0.9 to 1.28.
Homologues: Orthologues: chimpanzee NKIRAS1 (100% identical), guinea pig NKIRAS1 (98% identical), pig NKIRAS1 (98% identical), macaque NKIRAS1 (97% identical), rat Nkiras1 (96% identical), mouse Nkiras1 (95% identical), rabbit NKIRAS1 (95% identical), dog NKIRAS1 (85% identical), tropical clawed frog nkiras1 (77% identical), zebrafish nkiras1 (73% identical). Paralogues in human: NKIRAS2 (70% identical), RALB (30% identical), RRAS (30% identical), HRAS (29% identical), RRAS2 (29% identical), RASD2 (28% identical), RIT2 (28% identical), KRAS (28% identical), NRAS (28% identical), RALA (28% identical), RAP2A (28% identical), RAP2B (27% identical), and 23 more.
Diseases named in the same sentence as NKIRAS1 in open-access papers:
NKIRAS1 is named in the same sentence as 8 diseases in open-access papers, as found by Europe PMC text mining. Sharing a sentence is not in itself a finding about the gene and the disease. The quoted sentences say what the papers report.
kidney cancer (2 papers, 2012 to 2020). Primary or metastatic malignant neoplasm involving the kidney. "In addition, it is known that the copy number of NKIRAS1 is usually lower in RCC, and this gene is downregulated in malignant renal tumors." (PMID 33329723, 2020).
anaplastic glioma (1 paper, 2016). "Moreover, in IDH wild type anaplastic glioma patients NKIRAS1 expression was negatively correlated with miR-155 expression at the RNA level." (PMID 27880937, 2016).
ovarian carcinoma (1 paper, 2012). A malignant neoplasm originating from the surface ovarian epithelium. "A set of eight biomarkers: NKIRAS1/RPL15, THRB, RBPS3 (CTDSPL), IQSEC1, NBEAL2, ZIC4, LOC285205 and FOXP1, was identified as the most prominent set capable to detect both early and late stages of ovarian cancer." (PMID 23202957, 2012).
cancer (4 papers, 2012 to 2020). A tumor composed of atypical neoplastic, often pleomorphic cells that invade other tissues. "Furthermore, our results are confirmed by the literatures, with 6 out of top 10 features associated with specific cancers including NKIRAS1, CDKN2B, YTHDC2, MECOM, RBFOX1, and RAB6B." (PMID 33329723, 2020). "We selected novel epigenetic markers including NKIRAS1/RPL15, THRB RBPS3 (CTDSPL), IQSEC1, NBEAL2, ZIC4, LOC285205, CGGBP1, EPHB1 and FOXP1 that allowed detection of cancer in ovarian biopsies on all stages with sensitivity equal to (72 ± 11)% and specificity (94 ± 5)%." (PMID 23202957, 2012).
tumor (1 paper, 2017). "The tumor suppressor genes PTEN (Phosphatase and tensin homolog), JNK (c-Jun N-terminal kinase), RB1 as well as an additional inhibitor of NF-κB, NKIRAS1 (NF-κB inhibitor-interacting Ras-like protein 1) are among the putative miR-30e* targets." (PMID 28978058, 2017).
NKIRAS1 also shares sentences with these, for which no sentence is quoted: gastric carcinoma (1 paper); renal cell carcinoma (1); serous ovarian carcinoma (1).